MGAT2 (alpha-1,6-mannosyl-glycoprotein 2-beta-N-acetylglucosaminyltransferase)
Description:
Plays an essential role in protein N-glycosylation. Catalyzes the transfer of N-acetylglucosamine (GlcNAc) onto the free terminal mannose moiety in the core structure of the nascent N-linked glycan chain, giving rise to the second branch in complex glycans.
Synonyms: GNT-II; CDG2A; CDGS2; GLCNACTII; GNT2
Tractability: Small molecule: a structure with a bound ligand is known; a high-quality ligand is known. Antibody: UniProt predicts a signal peptide or a membrane-spanning region. PROTAC: ubiquitination databases record sites on it; its protein half-life has been measured; a small molecule that binds it is known.
Target class: Enzyme; Transferase
Chemical probes: CHEMBL3581716, TP-020 (high quality)
Gene: Protein-coding gene on chromosome 14 (49,620,799 to 49,623,481, forward strand). Ensembl gene ENSG00000168282.
Subcellular location: Golgi apparatus membrane
Subcellular location (Human Protein Atlas): Golgi apparatus
Pathways (Reactome):
Disease: Defective MGAT2 causes CDG-2a; Maturation of spike protein
Metabolism of proteins: Reactions specific to the complex N-glycan synthesis pathway
Gene Ontology:
Molecular function: alpha-1,6-mannosylglycoprotein 2-beta-N-acetylglucosaminyltransferase activity; manganese ion binding; protein homodimerization activity
Biological process: protein N-linked glycosylation; viral protein processing; oligosaccharide biosynthetic process
Cellular component: Golgi apparatus; Golgi membrane; membrane; Golgi stack
Genetic constraint (gnomAD): Loss-of-function variants: 17 observed, 34.44 expected, observed/expected ratio (o/e) 0.49, 90% interval 0.34 to 0.74. The upper end of that interval is the gene's LOEUF score, 0.74, which puts it in group 3 of 6, group 1 being the genes least tolerant of losing a copy. Missense variants: 529 observed, 585.26 expected, observed/expected ratio (o/e) 0.9, 90% interval 0.84 to 0.97. Synonymous variants: 248 observed, 242.48 expected, observed/expected ratio (o/e) 1.02, 90% interval 0.92 to 1.14.
Gene-disease validity (ClinGen):
ClinGen rates the evidence that MGAT2 causes each of these diseases.
MGAT2-congenital disorder of glycosylation (autosomal recessive): Moderate.
Homologues: Orthologues: macaque MGAT2 (97% identical), dog MGAT2 (94% identical), rabbit MGAT2 (92% identical), guinea pig MGAT2 (91% identical), pig MGAT2 (91% identical), rat Mgat2 (89% identical), mouse Mgat2 (89% identical), tropical clawed frog mgat2 (63% identical), zebrafish mgat2 (62% identical), Drosophila melanogaster Mgat2 (38% identical), Caenorhabditis elegans gly-20 (33% identical).
Diseases named in the same sentence as MGAT2 in open-access papers:
MGAT2 is named in the same sentence as 28 diseases in open-access papers, as found by Europe PMC text mining. Sharing a sentence is not in itself a finding about the gene and the disease. The quoted sentences say what the papers report.
Obesity (11 papers, 2012 to 2025). Accumulation of substantial excess body fat. "The anti‐obesity effects of MGAT2 inhibition are at least partially attributable to feeding suppression because MGAT2 deficiency decreases HFD intake in mice." (PMID 38090688, 2023). "Mice deficient in MGAT2 have the same phenotype as wild‐type mice under standard chow diet feeding conditions but are resistant to diet‐induced obesity under high‐fat diet (HFD) feeding conditions." (PMID 38090688, 2023). "When maintained on a high-fat diet (HFD), Mgat2-deficient mice were protected from HFD-induced obesity and insulin resistance." (PMID 22698140, 2012). "MGAT2 inhibition suppresses feeding behavior via peripheral vagus nerve signaling and may serve as a novel anti‐obesity strategy with a low risk of unexpected central nervous system‐related adverse effects." (PMID 38090688, 2023). "Therefore, MGAT2 is considered a promising pharmacological target for treating obesity and its associated diseases." (PMID 26938273, 2016). "In summary, the Mgat2-deficient mice are protected from HFD-induced obesity and insulin resistance." (PMID 22698140, 2012). "The inhibition of MGAT2 can suppress food intake in mice fed a high-fat diet through peripheral vagus nerve signaling and has potential as a novel anti-obesity strategy." (PMID 39065646, 2024). "With increasing investment in the anti-obesity market, monoacylglycerol acyltransferase 2 (MGAT2) is considered a pharmacological target for anti-obesity treatments." (PMID 39065646, 2024). "A decrease in lipid absorption in Mgat2 knockout mice has been shown to be protective against high-fat-diet-induced obesity and insulin resistance." (PMID 36430292, 2022). "Abcc10 gene knockout mice appear normal on a regular chow diet but are protected from high-fat-diet-induced obesity similarly to Mgat2 and Park2 knockout mice, and their plasma triglyceride levels are also decreased." (PMID 36430292, 2022). "Our data suggest several new beneficial aspects of pharmacological MGAT2 inhibition for improvement of obesity‐related metabolic diseases in mice." (PMID 31837122, 2020). "We have previously demonstrated that pharmacological inhibition of MGAT2 has beneficial effects on obesity and metabolic disorders in mice." (PMID 31837122, 2020). "Our results support MGAT2 activity inhibition as a potential therapeutic strategy to counteract human obesity, diabetes, and comorbidities related to abnormal lipid metabolism." (PMID 26938273, 2016). "In conclusion, the present study demonstrates that the selective and potent MGAT2 inhibitor compA remarkably ameliorates dyslipidemia, obesity, and diabetes." (PMID 26938273, 2016). "Monoacylglycerol O-acyltransferase 2 (MGAT2) catalyzes the synthesis of diacylglycerol (DG), a triacylglycerol precursor and potential peripheral target for novel anti-obesity therapeutics." (PMID 26938273, 2016). "And importantly, MGAT2 expression is up regulated in patients with obesity and NAFLD, and down regulated following gastric bypass surgery." (PMID 28943619, 2015). "Recently, some small-molecule MGAT2 inhibitors with significant structural diversity may be used to treat obesity and metabolic diseases further." (PMID 36817150, 2023). "Although further studies are required to clarify the detailed mechanisms of chronic pharmacological MGAT2 inhibition, our findings may inform the development of MGAT2‐targeting therapeutic drugs for obesity and obesity‐related diseases." (PMID 38090688, 2023). "Taken together, newly identified insights into the pharmacological effects of the MGAT2 inhibitor in this study further support the concept that pharmacological MGAT2 inhibition could be used as a treatment for obesity and its related metabolic diseases." (PMID 31837122, 2020).
Obesity (continued). "Here, we investigate the effects of MGAT2 inhibition on (a) fat‐induced gut peptide release and fat intake in normal mice and (b) metabolic disorders in ob/ob mice fed on a high‐fat diet, a model of severe obesity and type 2 diabetes, using a selective MGAT2 inhibitor." (PMID 31837122, 2020). "Our data demonstrated comparable anti-obesity effects of compA relative to MGAT2 genetic deletion." (PMID 26938273, 2016). "This suggests MGAT3 might play a more important role than MGAT2 in obesity related hepatic insulin resistance and NAFLD progression in humans." (PMID 28943619, 2015). "MGAT2 has a pivotal role in lipid metabolism in the small intestine, and the inhibition of MGAT2 activity may be a promising strategy for the treatment of obesity and type 2 diabetes." (PMID 22698140, 2012). "Taken together, the inhibition of MGAT2 may be a safer strategy than the inhibition of pancreatic lipase for the treatment of obesity." (PMID 22698140, 2012). "Therefore, an MGAT2 inhibitor could ameliorate unbalanced eating habits with fat palatability and reduction of high-fat food intake could contribute to the anti-obesity effects of the MGAT2 inhibitor." (PMID 26938273, 2016). "Because of the similar expression and function of MGAT2 in human and mice, MGAT2-knockout mice have been very useful in helping in the discovery of small molecule MGAT2 inhibitors aimed at treating several lipid-related maladies, such as obesity, hypertriglyceridemia, and T2D." (PMID 28943619, 2015). "Therefore, the Mgat2-deficient mice were protected from HFD-induced obesity independent of food intake." (PMID 22698140, 2012). "Thus, targeting MGAT2 for inhibition may have beneficial effects on obesity." (PMID 28943619, 2015). "Mice without global Mgat2 genes (Mgat2−/−) exhibited resistance to HFD-induced obesity, although they consumed and absorbed normal amounts of dietary fat." (PMID 36817150, 2023). "In this study, we revealed that pharmacological MGAT2 inhibition by CpdB modulated the release of anorectic gut peptides and intake of an HFD in normal mice and showed a beneficial effect on improvement of obesity and diabetes in HFD‐ob/ob mice." (PMID 31837122, 2020). "We anticipate that a MGAT2 inhibitor would ameliorate obesity and diabetes without PC-stimulated GI toxicity in clinical trials." (PMID 26938273, 2016). "Mice lacking MGAT2 are protected from obesity and insulin resistance induced by HFD." (PMID 26938273, 2016).
Hepatic steatosis (5 papers, 2015 to 2024). Steatosis is a term used to denote lipid accumulation within hepatocytes. "Selective MGAT2 inhibition can decrease gut TG synthesis, delay fat absorption, and decrease the risk of diarrhea while improving liver steatosis via weight loss." (PMID 38891828, 2024). "Concurrently, intestine-specific rescue of MGAT2 expression in MGAT2 KO mice almost completely reversed the amelioration of hepatic steatosis." (PMID 26938273, 2016). "Based on all the data accumulated thus far, the combined effects of MGAT2 inactivation in various tissues will have beneficial effects in reducing body weight, improving insulin resistance, decreasing hyperlipidemia, and attenuating hepatic steatosis." (PMID 28943619, 2015). "Under a high-fat diet, MGAT2-lacking mice showed better glucose tolerance and protected organisms from hepatic steatosis." (PMID 39327557, 2024).
Insulin resistance (5 papers, 2012 to 2023). Increased resistance towards insulin, that is, diminished effectiveness of insulin in reducing blood glucose levels. "Overexpression of ENPP1 in mice leads to insulin resistance and MGAT2 deficiency reduces lipid absorption and insulin resistance." (PMID 36858953, 2023). "Furthermore, our study demonstrated that genetic ablation of MGAT2 and compA improved HFD-STZ-induced hyperglycemia and insulin resistance." (PMID 26938273, 2016).
neuroblastoma (5 papers, 2017 to 2025). Neuroblastoma (NB) is the most common solid, extracranial childhood tumor. "For example, MGAT2 (GnT-II) overexpression in neuroblastoma increases N-glycan structures promoting cell proliferation and invasion." (PMID 40096084, 2025). "Our previous studies showed that the parental (NB_1) and N-glycan mutant (NB_1(-Mgat1), NB_1(-Mgat2), and NB_1(-Mgat3)) Neuroblastoma (NB) cell lines have compromised N-acetylglucosaminyltransferase activities: GnT-I, GnT-II, or GnT-III." (PMID 39736999, 2023). "Here, we investigated the role of N-acetylglucosaminyltransferase-II (GnTII, MGAT2) protein substrates in neuroblastoma (NB) cells." (PMID 32260356, 2020). "Previously, we engineered a neuroblastoma (NB_1) cell line with Mgat2 silenced, called the NB_1(-Mgat2) cell line." (PMID 29902282, 2018). "Using CRISPR/Cas9 technology, NB_1, a clonal cell line derived from rat neuroblastoma cells (NB), was modified to create an N-glycosylation mutant cell line, NB_1 (-Mgat2), which expresses predominantly hybrid type N-glycans." (PMID 30271698, 2017). "This was investigated by silencing the Mgat2 gene in rat B35 neuroblastoma (NB) cells by employment of the CRISPR/Cas9 technology." (PMID 30271698, 2017). "Previously, we silenced Mgat2 in neuroblastoma (NB) cells, which halted the conversion of hybrid type N-glycans to complex type, to generate a novel cell line, NB_1(-Mgat2)." (PMID 29902282, 2018).
diabetes (2 papers, 2016 to 2020). "MGAT2 inhibition by CompA under severe diabetes ameliorated hyperglycemia and fatty liver in HFD-streptozotocin (STZ)-treated mice." (PMID 26938273, 2016).
dyslipidemia (2 papers, 2015 to 2016). "Another possible indication of MGAT2 inhibitors is treatment of dyslipidemia caused by genetic disorders." (PMID 26938273, 2016). "Amelioration of postprandial dyslipidemia by MGAT2 inhibition is one possible mechanism for improving insulin sensitivity via attenuation of ectopic lipotoxicity in peripheral tissues." (PMID 26938273, 2016). "Inactivation of MGAT2 by genetic manipulation and pharmacological intervention supports the idea that targeting the MAG pathway as a therapeutic for metabolic syndrome is a viable option for inhibiting intestinal TAG synthesis." (PMID 28943619, 2015).
hypertriglyceridemia (2 papers, 2015 to 2023). A laboratory test result indicating elevated triglyceride concentration in the blood. "The rs115505361 is mapped on MGAT2 and associated with body mass index, blood proteins, insulin sensitivity and hypertriglyceridemia." (PMID 37669986, 2023).
breast carcinoma (1 paper, 2022). "In breast cancer, MGAT1, MGAT2 and MGAT3 were downregulated, but MGAT4A, MGAT4B, and MGAT5 were increased." (PMID 36185271, 2022).
carbohydrate-deficient glycoprotein syndrome, type II (1 paper, 2025). "Mutations in MGAT2 gene can lead to MGAT2-CDG, also known as carbohydrate-deficient glycoprotein syndrome, type II." (PMID 41583011, 2025).
Failure to thrive (1 paper, 2021). Failure to thrive (FTT) refers to a child whose physical growth is substantially below the norm. "Humans with point mutations in the catalytic domain of Mgat2, which encodes GnTII, have a congenital disorder of glycosylation type IIa, a syndrome characterized by a general failure to thrive, dysmorphic facial features, feeding difficulties, and psychomotor retardation." (PMID 34804097, 2021).
Glucose intolerance (1 paper, 2012). Glucose intolerance (GI) can be defined as dysglycemia that comprises both prediabetes and diabetes. "When maintained on an HFD, Mgat2+/+ mice showed an expected increase in blood glucose, insulin, and total cholesterol levels as well as in glucose intolerance." (PMID 22698140, 2012).
Hepatic fibrosis (1 paper, 2022). The presence of excessive fibrous connective tissue in the liver. "HSC activation produces hepatic fibrosis, and glycoproteins appear as indicators of the disease (increased MGAT2 level)." (PMID 35865277, 2022).
infertile (1 paper, 2024). "RNA-seq comparisons of 15-day Mgat2 cKO germ cells identified biological processes and molecular networks that provide insights into the spermatogenic defects in Mgat2 cKO infertile male subjects." (PMID 39364139, 2024).
Salmonella Infections (1 paper, 2023). Infections with bacteria of the genus SALMONELLA. "Genetic deletion of Mgat2 enhanced TCR signaling and reactivity of old-female CD4+ T cells and Mgat2-deficient T cells exhibited greater capacity to eliminate salmonella infection due to greater TH17 differentiation when compared to wild-type CD4+ T cells from old females." (PMID 38027254, 2023).
steatosis (1 paper, 2015). Increased lipid within the cytoplasm of cells. "It is also possible that inhibition of the MGAT2 isozyme in the liver will improve steatosis by attenuating fat accumulation and insulin resistance." (PMID 28943619, 2015).
metabolic disorders (6 papers, 2012 to 2025). "To determine the physiological importance of MGAT2 in metabolic disorders and lipid metabolism in the small intestine, we constructed and analyzed Mgat2-deficient mice." (PMID 22698140, 2012). "Such that Mgat2‐deficient mice show increased energy expenditure and protection from metabolic disorders, highlighting that downregulation of these genes may act as a protective mechanism." (PMID 40035569, 2025). "With that said, these results do indicate that targeting MGAT2 for small molecule discovery will be efficacious, and that adult patients with various metabolic disorders will respond to treatment." (PMID 28943619, 2015). "Heterozygote (Mgat2+/−) mice had an intermediate phenotype between Mgat2+/+ and Mgat2−/− and were partially protected from metabolic disorders." (PMID 22698140, 2012). "Heterozygote (Mgat2+/−) mice had an intermediate phenotype between Mgat2+/+ and Mgat2−/− and were partially protected from metabolic disorders, indicating a gene dosage-dependent effect of Mgat2 and feasibility of MGAT2 as a potential drug target." (PMID 22698140, 2012). "However, a limited number of studies have reported on the efficacy of pharmacological MGAT2 inhibition for metabolic diseases in preclinical studies." (PMID 31837122, 2020). "Moreover, the deletion of MGAT2 increases the level of gut incretin glucagon-like peptide-1 (GLP-1), which has many beneficial effects in treating metabolic disorders including stimulating insulin secretion, reducing glucagon, slowing gastric emptying, and inducing satiety." (PMID 28943619, 2015). "Recently, it was reported that mice lacking Mgat2 are protected from metabolic disorders induced by high-fat feeding and show increased energy expenditure, suggesting that MGAT2 may be a key determinant of fat absorption and energy metabolism." (PMID 22698140, 2012).
cancer (4 papers, 2020 to 2025). A tumor composed of atypical neoplastic, often pleomorphic cells that invade other tissues. "Of interest, 3 GT families stood out in cancer cells after their interaction with platelets: MGAT2, MGAT3 and B3GNT which were significantly overexpressed by 343, 320 and 170%, respectively." (PMID 40096084, 2025).
neoplasia (2 papers, 2017 to 2025). "Notably, neoplasia patients exhibited a tendency to upregulate several glycogenes, including MGAT1, MAN2A1, MAN2B1, and MGAT2 (which contributed to the clustering), associated with the initial steps of the biosynthesis of more complex N-glycan structures." (PMID 40087977, 2025).
infection (1 paper, 2024). The state of being infected such as from the introduction of a foreign agent such as serum, vaccine, antigenic substance or organism. "Compared to mock-infected cells, AIV infection significantly upregulated the expression of ST3GAL6 and MGAT2 genes at 12-, 24-, 36-, and 48-hours post-infection, and ST3GAL1 gene at 24-, 36-, and 48-hours post-infection, while B4GALT1 expression remained largely unchanged." (PMID 39652582, 2024).
MGAT2 also shares sentences with these, for which no sentence is quoted: type 2 diabetes (2 papers); colon cancers (1); genetic disorders (1); Hypercholesterolemia (1); Hyperglycemia (1); hyperlipidemia (1); Hypertension (1); memory impairment (1); nonalcoholic steatohepatitis (1).